VDR (vitamin D receptor)
Diseases named in the same sentence as VDR in open-access papers (continued):
Sharing a sentence is not in itself a finding about the gene and the disease.
Insulin resistance (continued). "Thus, our study highlights the possible role of VDR BsmI polymorphism in mediating insulin resistance in early adolescence in non-Caucasian populations." (PMID 28617856, 2017). "The VDR gene may modify the relationship between vitamin D and insulin resistance." (PMID 28617856, 2017). "Thus, the nuclear receptor VDR is expressed in pancreatic cells, is involved in regulating insulin resistance, secretion, and inflammation of pancreatic islets, and may accordingly play a role in pathogenesis of T2D." (PMID 26699871, 2015). "Individuals with MetSyn and heterozygosis for VDR 2228570 C > T have higher concentrations of iPTH and HOMA β than those without this polymorphism, and subjects with recessive homozygosis for the same polymorphisms presented higher insulin resistance than those with the heterozygous genotype." (PMID 23855914, 2013). "Furthermore, vitamin D might decrease insulin resistance in peripheral insulin-target cells through the vitamin D receptor found in adipocytes, muscle, and hepatocytes while also promoting the expression of insulin receptors and improving insulin responsiveness for glucose transport." (PMID 40813680, 2025). "Serum 25-hydroxyvitamin D ([25 [[OH]] D) has been demonstrated to have a negative influence on VDR-mediated insulin resistance via regulating the expression of target genes." (PMID 35958959, 2022). "In addition, RXRs are members of the vitamin D (VD) pathway that regulate the transcription of vitamin D receptor (VDR) and helps to repair islet β cells, improve insulin resistance and promote the glucose and lipid metabolism." (PMID 34633445, 2021). "Based on this, the interaction between VDR, RXR and their ligands could play a relevant role in the pathophysiology of insulin resistance." (PMID 34684492, 2021). "A genetic variation in the VDR may affect PCOS development, as well as insulin resistance in women with PCOS." (PMID 34684492, 2021). "Serum 25-hydroxyvitamin D [25 (OH) D] has been shown to have a negative effect on VDR-mediated insulin resistance by regulating the expression of target genes." (PMID 30764792, 2019). "A positive significant association of ff carriers of VDR was also shown (FokI polymorphism) (P = 0.02) and negative association of 148insG carriers of PTPN1 (148insG polymorphism) (P = 0.041) with insulin resistance index." (PMID 26587547, 2015). "Polycystic ovary syndrome (PCOS) is known as a metabolic disorder.The results of recent studies implied that vitamin D receptor (VDR) geneticvariants may impact PCOS and insulin resistance in women with PCOS." (PMID 24520473, 2013). "Furthermore, mice lacking a functional vitamin D receptor show impaired insulin secretory capacity together with insulin resistance." (PMID 35406129, 2022). "Notably, it seems that vitamin D, the ligand of VDR, is not required for the role of VDR in glucocorticoid and TNFα induced insulin resistance." (PMID 30310815, 2018).
type 2 diabetes (78 papers, 2010 to 2026). "Greater understanding of the effects of VDR gene polymorphism on the pathogenesis of type 2 diabetes and metabolic syndrome is required." (PMID 39861482, 2025). "Variations in the vitamin D receptor gene in Emiratis has also been associated with the susceptibility to type 2 diabetes." (PMID 39165779, 2024). "Another cross-sectional study from the UAE investigated the association between VDR polymorphisms and type 2 diabetes (T2DM) among 264 patients with T2DM, and 91 healthy controls were enrolled." (PMID 37189820, 2023). "VDR deficiency results in impaired autophagy and enhanced cell death, particularly in cardiomyopathy, type 2 diabetes, ischemia-reperfusion injury, microbial infections, and cancers." (PMID 35047105, 2022). "Our group investigated the association of genetic variants within VDR and other genes important in vitamin D metabolism with type 2 diabetes among Emiratis and concluded that a strong association existed with risk of disease for specific variants." (PMID 34835935, 2021). "Only one study has reported that the variant at VDR-rs11568820 impairs the secretion of pancreatic islets and increases the risk of type 2 diabetes in the adult cohort and PG2H in children." (PMID 34959770, 2021). "We investigated the possible association of VDR polymorphisms (FokI, TaqI, BsmI, and ApaI) with susceptibility/ resistance against the development of type 2 diabetes." (PMID 31793694, 2020). "Studies showing an association between VDR polymorphisms and susceptibility to type 2 diabetes have been inconsistent." (PMID 24557774, 2014). "VDR polymorphisms may also be associated with risk factors for cardiovascular disease, myocardial infarction, and type 2 diabetes." (PMID 37375641, 2023). "However the opposed results indicated that the haplotype comprising the minor allele of BsmI, major allele of ApaI and minor allele of TaqI of VDR (AAC) was associated with an increased risk of CAD in type 2 diabetes patients." (PMID 29108239, 2017). "Certain vitamin D binding proteins and allelic variations in the vitamin D receptor gene might also affect insulin secretion and glucose tolerance, which, in turn, might contribute to the genetic risk of type 2 diabetes." (PMID 27413370, 2016). "Although not uniformly, it was suggested that several genetic polymorphisms in genes related to vitamin D metabolism, such as DBP and VDR, may predispose subjects to type 2 diabetes." (PMID 22347618, 2012). "VDR polymorphisms were also associated with type 2 diabetes in two Indian case-control studies." (PMID 22347618, 2012). "The present study was performed to evaluate the association of VDR gene rs739837 and type 2 diabetes (T2DM) or gestational diabetes mellitus (GDM) risk." (PMID 35526059, 2022). "Findings from other studies, such as an inverse association between 1,25(OH)2D levels and chronic kidney disease in patients with type 2 diabetes that was significantly modified by FokI, support the notion that vitamin D and/or polymorphisms in the VDR may be important in diabetic physiopathology." (PMID 24557774, 2014). "We established the murine models by employing type 2 diabetes db/db mice to investigate the effect of VDR activation on renal function in DN." (PMID 38145959, 2024). "VDR-rs11568820 not only plays an important role in the development of type 2 diabetes, but also of GDM." (PMID 34959770, 2021). "VDR has effect on proliferation, differentiation, and activation of immune cells and cytokine production, and subsequently type 2 diabetes occurs." (PMID 31114636, 2019). "Selective vitamin D receptor activator paricalcitol effectively reduce proteinuria in patients with type 2 diabetes through inhibition of the renin-angiotensin-aldosterone system (RAAS)." (PMID 26109389, 2015).
type 2 diabetes (continued). "The VDR gene (encoding as SNPs p.BsmI, p.ApaI, p.TaqI, and p.FokI), and, HNF1A gene (encoding as SNPs p.I27L, p.A98V, and p.S487N) were chosen because these genetic variants have been reported to be associated with type 2 diabetes, as well as GDM risk." (PMID 31114636, 2019). "The role of VDR gene polymorphism and type 2 diabetes has been studied, but the results are not consistent among different populations." (PMID 26047339, 2015). "We aimed to examine associations among serum 25-hydroxyvitamin D (25OHD) levels, 1,25-dihyroxyvitamin D (1,25OHD) levels, vitamin D receptor (VDR) polymorphisms, and renal function based on estimated glomerular filtration rate (eGFR) in patients with type 2 diabetes." (PMID 23226566, 2012). "Furthermore, studies in patients with type 2 diabetes suggested that vitamin D intake increases circulating ghrelin; whether VDR has a role in the differentiation of ghrelin-cells (X) remains to be tested." (PMID 41117135, 2025). "They showed that the interaction of BRD7 with VDR ultimately leads to inhibition of BRD9 activity in β cells, which in turn reverses β cell dysfunction and reduces blood glucose levels in type 2 diabetic mouse models." (PMID 30926848, 2019). "In RCT of selective vitamin D receptor activation with paricalcitol for reduction of albuminuria in patients with type 2 diabetes (VITAL study), paricalcitol could not demonstrate an additional effect in decreasing albuminuria in DN patients." (PMID 28088187, 2017).
tuberculosis (72 papers, 2006 to 2025). A chronic, recurrent infection caused by the bacterium Mycobacterium tuberculosis. "Various single nucleotide polymorphisms (SNPs) of the VDR gene have been studied, and some of them showed an association between susceptibility/resistance to tuberculosis." (PMID 38398882, 2024). "The VDR gene polymorphisms ApaI, BsmI, TaqI, and FokI have been studied in many infections including toxoplasmosis, tuberculosis, and T. cruzi." (PMID 37319132, 2023). "According to research on VDR gene variants in other infectious diseases, FokI has been linked to tuberculosis in populations of various ethnic backgrounds, albeit the findings are conflicting." (PMID 37319132, 2023). "In fact, vitamin D deficiency and vitamin D receptor polymorphism have shown to affect human susceptibility to tuberculosis, and vitamin D-based oxysterols can promote clinical improvements in tuberculosis patients." (PMID 29326713, 2017). "In tuberculosis (TB), associations with both the minor and major allele of the VDR SNP were found in different studies." (PMID 26894582, 2016). "Regarding the study of VDR gene polymorphisms in other infectious diseases, rs2228570 has been associated with tuberculosis in populations of different ethnicities, although the results are contradictory." (PMID 27502545, 2016). "Genetic polymorphism in Mannose Binding Lectin-2 (MBL-2) and Vitamin D Receptor (VDR) is known to influence the susceptibility to tuberculosis." (PMID 26693353, 2015). "The study needs to be validated in larger samples to get a clearer picture of frequency distribution of MBL-2 and VDR genetic variants and their association to tuberculosis susceptibility in different parts of India." (PMID 26693353, 2015). "The present study involved the frequency distribution analyses of MBL-2 and VDR polymorphisms, two molecules known to play a key role in tuberculosis susceptibility." (PMID 26693353, 2015). "The association between vitamin D receptor (VDR) FokI polymorphism and tuberculosis (TB) risk remains a matter of debate." (PMID 26705207, 2015). "Work in a similar Peruvian population has demonstrated that vitamin D receptor polymorphisms were associated with tuberculosis patients' time to sputum culture conversion." (PMID 24596279, 2014). "In a case-control study in The Gambia, two candidate genes, natural resistance associated macrophage protein (NRAMP1) and VDR, were found to be associated with tuberculosis." (PMID 25202468, 2014). "Basic information of qualified cases-control studies on vitamin D receptor gene polymorphisms for tuberculosis." (PMID 24349552, 2013). "Due to underpowered design or small study sample size, previous studies have not reached a consensus regarding the association between the VDR gene variants and tuberculosis risk." (PMID 24349552, 2013). "In contrast, presence of the f allele of the FokI VDR polymorphism is associated with reduction in anti-infective action against tuberculosis." (PMID 22682426, 2012). "Single nucleotide polymorphisms in the VDR confer increased susceptibility to tuberculosis, suggested a key role for VDR activation in host defense against tuberculosis in humans." (PMID 19503839, 2009). "In children with active tuberculosis, there was more VDR DNA methylation, that was associated with reduced VDR expression and could be associated with increased susceptibility to tuberculosis." (PMID 36246903, 2022). "In addition, the presence of an association between vitamin D receptor (VDR) and lipid metabolism in human tuberculosis and infected macrophages has also been reported." (PMID 31058102, 2019). "Single nucleotide polymorphisms (SNPs) in VDR may influence the function of vitamin D and susceptibility to tuberculosis." (PMID 27595605, 2016). "Interestingly, the VDR SNP rs10735810 has also been shown to be associated with susceptibility to tuberculosis and RSV bronchiolitis in children." (PMID 26894582, 2016).
tuberculosis (continued). "The polymorphism in the VDR gene may influence the VDR activity, subsequently associating it with increased susceptibility to tuberculosis and various clinical outcomes." (PMID 26693353, 2015). "The four most commonly investigated VDR polymorphisms in association with different diseases, including susceptibility to tuberculosis, are located in exon 2 (rs2228570 or FokI), intron 8 (rs1544410 or BsmI and rs7975232 or ApaI), and exon 9 (rs731236 or TaqI)." (PMID 29805861, 2013). "Summary of VDR gene genotypes on the risk of tuberculosis in different ethnicities." (PMID 24349552, 2013). "Thus, because previous results were inconsistent and more ethnic background needed to be added, it was necessary to carry out this meta-analysis on the relationship between hot spot variants of the VDR gene and the risk of tuberculosis." (PMID 24349552, 2013). "In summary, we explored potential associations between SNPs in the VDR (FokI, ApaI) gene and susceptibility to tuberculosis in the Kazakh Population, which requires further detailed analysis with a larger sample size and greater geographic diversity including other regions of Kazakhstan." (PMID 29805861, 2013). "Some studies have reported interactions between VDR polymorphisms and 25OHD in diseases such as colorectal adenoma and tuberculosis, although to our knowledge, this is the first time an interaction between VDR polymorphisms and 1,25OHD levels has been reported in diabetic patients with CKD." (PMID 23226566, 2012). "However, the association between TaqI and FokI VDR gene polymorphisms and susceptibility to tuberculosis is still controversial." (PMID 23144845, 2012). "Several studies have also investigated the role of VDR polymorphisms in tuberculosis (TB) susceptibility across diverse ethnic groups." (PMID 40278307, 2025). "In addition, vitamin D receptor genetic polymorphism, vitamin D binding protein, BMI and degree of tuberculosis transmission may be confusion factors." (PMID 25938683, 2015). "In this meta-analysis of the relationship between the VDR gene polymorphisms and the risk of tuberculosis, we found that the FokI SNP in the recessive model (ff vs. Ff/FF) significantly increased the risk of tuberculosis, and the risk effect was found in the Chinese population." (PMID 24349552, 2013). "Genetic variations in vitamin D receptor (VDR) may contribute to tuberculosis (TB) risk." (PMID 23825591, 2013). "In conclusion, this meta-analysis study evaluated the relationship between the VDR gene hot spot SNPs and the risk of tuberculosis in twenty-nine case-control studies, and provided evidence that the FokI SNP might increase the risk of tuberculosis in a recessive model." (PMID 24349552, 2013). "Four potentially functional single nucleotide polymorphisms (SNPs) of the VDR gene (ApaI, SNP ID: rs7975232; BsmI, SNP ID: rs1544410; FokI, SNP ID: rs2228570; and TaqI, SNP ID: rs731236) have been main focus in relation to the risk of tuberculosis compared to other SNPs." (PMID 24349552, 2013). "Additionally, VDR gene polymorphisms could be linked to each other and to other unidentified genes, which could also be important for tuberculosis risk." (PMID 24349552, 2013). "Furthermore, susceptibility to infection by tuberculosis may be altered by variations in the vitamin D receptor gene." (PMID 16608528, 2006). "TB is caused by Mycobacterium tuberculosis infection, and its elimination depends on the expression of several antimicrobial peptides and cytokines, which are activated by the VDR." (PMID 38203278, 2023). "Polymorphisms in genes for the Toll-like receptor (TLR), interleukin (IL), vitamin D receptor (VDR) and interferon-gamma (IFN-γ) are associated with susceptibility to tuberculosis." (PMID 28693442, 2017).
tuberculosis (continued). "Analysis of gene polymorphisms of NRAMP1 gene (3′UTR, 274CT) and VDR gene (Fok1 and Taq1) was done by using Polymerase chain reaction-restriction fragment length polymorphism (PCR-RFLP) in Tuberculosis (TB) patients and healthy controls." (PMID 28583097, 2017). "There is an emerging scientific literature in the area of tuberculosis and vitamin D status that has identified genetic variations in the vitamin D receptor, demonstrating variation in the induction of genes of the immune system in response to vitamin D." (PMID 25849649, 2015). "Genetic polymorphism in Mannose Binding Lectin-2 (MBL-2), a central player in the innate immune response and Vitamin D Receptor (VDR), an immunomodulator has been found to influence the susceptibility to tuberculosis." (PMID 26693353, 2015). "Low vitamin D concentrations contribute to an increased risk of tuberculosis contacts' tuberculin skin test (TST) converting to positive and a higher likelihood of active tuberculosis disease in people with specific vitamin D receptor polymorphisms." (PMID 24596279, 2014). "Across populations, single nucleotide polymorphisms (SNPs) in the VDR have been associated inconsistently with diseases of diverse etiology, including tuberculosis (TB), multiple sclerosis, systemic lupus erythematosus (SLE), cirrhosis and various types of cancer." (PMID 23805323, 2013). "However, epigenetic factors such as methylation regulate VDR expression in tuberculosis patients, and non-coding RNAs affect the levels and function of VDR." (PMID 39335504, 2024). "Indeed, we have previously shown ethnicity-dependent methylation of VDR CGI 1060 to distinguish tuberculosis cases from controls." (PMID 28959253, 2017). "While the data are not conclusive, in tuberculosis these VDR polymorphisms have been associated with serum 25(OH)D concentrations and responses to vitamin D therapy." (PMID 25849649, 2015). "Unfortunately, the results have been conflicting and still the role of VDR in tuberculosis susceptibility is not clear: the polymorphism determines susceptibility to the development of clinical disease or susceptibility to infection." (PMID 26693353, 2015). "The results suggest the absence of any association between VDR variants FokI, ApaI, and TaqI and susceptibility to tuberculosis." (PMID 26578819, 2015). "The other three SNPs of the VDR gene showed no notable associations with tuberculosis risk in the pooled samples." (PMID 24349552, 2013). "In particular, functional/putatively functional SNPs in genes that affect macrophage anti-mycobacterial activity (e.g., vitamin D receptor [VDR], monocyte chemoattractant protein [MCP–1], and interferon [IFNγ]) associate with increased risk for and severity of tuberculosis in various ethnic groups." (PMID 21339808, 2011). "Importantly, miR30d-5p, together with miR27a-3p, could inhibit VDR involved in the progression of tuberculosis." (PMID 39334706, 2024). "There was increased macrophage expression of VDR after stimulation with live M. tuberculosis in persons with previous extrapulmonary TB." (PMID 31039752, 2019). "VDR gene polymorphisms have been extensively studied for their potential association with susceptibility to different autoimmune and inflammatory disorders, for example, MS, T1D, RA, systemic lupus erythematosus (SLE), inflammatory bowel diseases, or tuberculosis." (PMID 31531369, 2019). "The increased expression of VDR and IL-1β in persons with previous extrapulmonary TB suggests that even after successful anti-mycobacterial therapy, their macrophages remain “primed” and demonstrate a brisk response after re-stimulation with M. tuberculosis." (PMID 31039752, 2019). "Status of Fok I VDR polymorphism along with vitamin D, Vitamin D receptor (VDR), and cathelicidin levels in Tuberculosis (TB) patients compared to household contacts and implication of these findings in susceptibility to TB is not known." (PMID 31649297, 2019).